SMAD4 (SMAD family member 4)
Diseases named in the same sentence as SMAD4 in open-access papers (continued):
Sharing a sentence is not in itself a finding about the gene and the disease.
colitis (continued). "Here, we show that Smad4 deprivation enhances the expression of TGF‐β1 and YAP, and YAP in turn interacts with Smad2/3 and exacerbates the development of colitis and CAC." (PMID 37261975, 2023). "Recent investigations into DSS-induced colitis have unveiled dynamic expression patterns correlating with disease progression, notably observing an upregulation of BMP4 and Smad4 in the crypt during the early stages, followed by a downregulation in the later stages." (PMID 37628872, 2023). "In the present study, our results showed that upregulated SMAD4 and BMP4 expression was related to a more rapid colon epithelium renewal and Lgr5+ ISC maintenance ability during the first 3 days of DSS induced experimental colitis in mice." (PMID 34692671, 2021). "The authors showed that mice with deletion of Smad4 in the intestinal epithelium presented macroscopic invasive adenocarcinomas of the distal colon and rectum following chronic DSS-induced experimental colitis." (PMID 33375423, 2020). "Consistently, 2‐month‐old Smad4−/−/Yap+/−/Taz+/− mice displayed reduced diarrhea and less rectal bleeding compared to their control littermates in the DSS‐induced colitis mice (data not shown)." (PMID 37261975, 2023).
colorectal adenocarcinoma (14 papers, 2011 to 2025). The most common type of colorectal carcinoma. "Chromosome 18q is the location of the DCC, DPC4 (SMAD4; MADH4), and JV-18 (SMAD2; MADH2) genes, and loss is frequent in colorectal adenocarcinoma." (PMID 37509254, 2023). "Hence, we used a KRAS- and SMAD4-wild-type colorectal adenocarcinoma cell line, SW48, and its genetically engineered derivative carrying the activating KRASG12D allele." (PMID 35008475, 2021). "Three of the twenty-one genes predicted to be affected by these miRNAs—SMAD2, SMAD4, and TGFBR2—were shared between pathways related to colorectal adenocarcinoma (COAD) and TGF-β signaling." (PMID 40868288, 2025). "Frequent genetic mutations found in colorectal adenocarcinoma are not exhibited by GCA, which are usually negative for BRAF, KRAS and SMAD4." (PMID 40729214, 2024).
osteosarcoma (14 papers, 2016 to 2023). A usually aggressive malignant bone-forming mesenchymal neoplasm, predominantly affecting adolescents and young adults. "Instead, it is reported that USP17 is upregulated in osteosarcoma and promotes cell proliferation, metastasis, and epithelial–mesenchymal transition by stabilizing SMAD4." (PMID 37894935, 2023). "Downregulation of miR-574-3p induced in osteosarcoma revealed that SMAD4, as a target of miR-574-3p, rescued cells from the tumor growth promoting effect of miR-574-3p." (PMID 33660570, 2021). "SNHG7 also effectively blocked miR-34a-mediated targeting of SMAD4 to enhance metastasizing potential of osteosarcoma cells." (PMID 33511320, 2021). "Different oncogenic lncRNAs promoted the expression of SMAD4 to enhance proliferation capacity of osteosarcoma cells." (PMID 33511320, 2021). "A recent study has found that the overexpression of p-Smad2, p-Smad3, and Smad4 increased caspase 3 and caspase 9 activation in osteosarcoma cells." (PMID 32126993, 2020). "Another example is candidate microRNA 2, predicted to bind SMAD2 and SMAD4, genes already related with Osteosarcoma, and resulting potentially interesting for further in vitro studies." (PMID 31816885, 2019). "In conclusion, we revealed that enhanced MALAT1 expression predicted unfavourable outcome in osteosarcoma and promoted cell proliferation through suppressing miR-205 and activating SMAD4 function." (PMID 29290978, 2017). "Subsequently, the downstream gene SMAD4 was identified as a direct functional target of miR-205, and miR-205 suppressed osteosarcoma cell growth through suppressing SMAD4." (PMID 29290978, 2017). "More importantly, MALAT1 promoted osteosarcoma cell proliferation through suppressing miR-205 and activating SMAD4 signaling." (PMID 29290978, 2017). "Collectively, we demonstrated that MALAT1 promotes cell proliferation through suppressing miR-205 and promoting SMAD4 expression in osteosarcoma." (PMID 29290978, 2017). "More importantly, overexpression of miR-205 significantly suppressed SMAD4 expression level in osteosarcoma cells, and Dual-Luciferase reporter assay further indicated a direct binding of miR-205 on SMAD4 3’UTR region." (PMID 29290978, 2017). "SMAD4 played critical role in the proliferation and metastasis of osteosarcoma cells." (PMID 33511320, 2021). "SMAD4 was identified as a functional target gene of miR-205 in osteosarcoma." (PMID 29290978, 2017). "We found that miR-205 was negatively correlated with SMAD4 expression in osteosarcoma tissues." (PMID 29290978, 2017). "USP17 interacts with Smad4 to stabilize Smad4 through its DUB activity and then promotes EMT to enhance the migration and invasion of osteosarcoma cells." (PMID 34454495, 2021). "USP17 is upregulated in osteosarcoma tissues and stabilizes SMAD4 through its DUB activity, leading to enhanced osteosarcoma cell invasion." (PMID 32268558, 2020). "We performed luciferase reporter assay with a vector containing the putative SMAD4 3’-UTR target site downstream of the luciferase reporter gene, which was transfected into osteosarcoma cells." (PMID 29290978, 2017). "It has proved that SNHG7 was able to regulate osteosarcoma (OS) cell vitality, migration, and invasion by activating sponging miR-34a, which targeted and suppressed the epithelial-mesenchymal transition (EMT) through the TGF-β/SMAD4 signaling pathway." (PMID 34714775, 2021). "RT-qPCR showed that SMAD4 mRNA was up-regulated in primary osteosarcoma tissues, and a significant negative correlation was also found between SMAD4 and miR-205 expression in 64 osteosarcoma tissues (r=-0.85, P<0.0001)." (PMID 29290978, 2017). "We demonstrate the utility of this resource by using it to predict the drug sensitivity of genetically or histologically defined subsets of tumor cell lines, including an increased sensitivity of osteosarcoma cell lines to FGFR inhibitors and SMAD4 mutant tumor cells to mitotic inhibitors." (PMID 26947069, 2016).
osteosarcoma (continued). "Additionally, immunohistochemistry analysis indicated that SMAD4 protein was significantly enriched in primary osteosarcoma when compared with noncancerous tissues." (PMID 29290978, 2017).
oral squamous cell carcinoma (13 papers, 2013 to 2025). "EP300, a histone acetyltransferase, regulates gene expression and has been implicated in oral squamous cell carcinoma progression through TGF‐β/Smad4 signaling." (PMID 41312415, 2025). "In oral squamous cell carcinoma cells, overexpression of sirtuin-1 results in a decrease in acetylated SMAD4 and an inhibition of TGF-β–mediated cell migration." (PMID 35203583, 2022). "The effect of SIRT1 in EMT phenotype though SMAD4 deacetylation has also been reported in oral squamous cell carcinoma." (PMID 32340156, 2020). "In this study, we demonstrated that SIRT1 suppresses the EMT process in oral squamous cell carcinoma cells by deacetylating Smad4 and repressing MMP7 expression." (PMID 25424420, 2014). "We found that increased levels of SIRT1 in oral squamous cell carcinoma tissue contributing to decreased Smad4 acetylation and repressed MMP7 activity." (PMID 25424420, 2014). "RNA interference was used to knockdown either SIRT1 or Smad4 expression in oral squamous cell carcinoma (OSCC) cell lines." (PMID 25424420, 2014). "This study explores the complex relationship between SMAD4 and epithelial–mesenchymal transition (EMT) in oral squamous cell carcinoma (OSCC)." (PMID 40507242, 2025).
squamous cell carcinoma (13 papers, 2011 to 2025). A carcinoma arising from squamous epithelial cells. "SMAD4 loss is a biomarker of squamous cell carcinoma and is used for its prognosis and prediction of treatment response." (PMID 36875704, 2023). "The DNA damage and genomic instability caused by SMAD4-deletion results in poor survival and drug resistance in patients with squamous cell carcinoma of the head and neck." (PMID 37035326, 2023). "And the loss of Smad4 expression is also found in squamous cell carcinoma of the head and neck and esophageal squamous cell carcinoma, and the low expression of Smad4 is closely related to the aggressive behavior of these two tumors." (PMID 33794845, 2021). "SMAD4 deletion spread metastatic squamous cell carcinomas and associated with lung metastasis and EMT in transgenic mice model." (PMID 30745456, 2019). "Epithelial deficiency of Smad4 could lead to overexpression of TGF‐β which then was released into the tumour microenvironment to promote squamous carcinoma progression through pro‐inflammatory and immune evasion mechanisms." (PMID 37563869, 2023). "Histological analysis showed that the expression of Smad4 in adenocarcinoma was lower than that in squamous cell carcinoma." (PMID 33794845, 2021). "Zeng et al13 reported the suppression of SMAD4 by miR‐205 regulates TGF‐β‐induced EMT in Squamous cell carcinoma cell lines." (PMID 30741461, 2019). "Because previous studies clearly reported that SMAD4 loss or reduction is found in squamous cell carcinomas (SCCs) in different tissues including OSCC 16, 17, we focused on SMAD4 expression in precancerous lesions." (PMID 28256094, 2017). "Further, conditional knockout of Smad4 through MMTV-Cre mediated recombination leads to squamous cell carcinoma formation." (PMID 22168923, 2011). "We co‐transfected circLDLRAD3 and Smad4 in squamous carcinoma cells and showed that Smad4 could restore the effect of circLDLRAD3 on cell functions." (PMID 37563869, 2023). "In contrast, no prognostic significance was seen in FSTL1, BMP4, and Smad4 IHC expression in squamous cell carcinoma." (PMID 28852126, 2017).
biliary tract cancer (12 papers, 2002 to 2026). "In COSMIC cohort studies, point mutations of SMAD4 were identified in 0.21, 2.24, 2.46, and 8.86% of kidney, lung, esophagus, and biliary tract cancers, respectively." (PMID 31867281, 2019). "In biliary tract cancer, SMAD4 was the more frequent mutated gene." (PMID 35911441, 2022).
Familial adenomatous polyposis (12 papers, 2010 to 2025). Familial adenomatous polyposis (FAP) is characterized by the development of hundreds to thousands of adenomas in the rectum and colon during the second decade of life. "NGS can identify gene mutations such as APC, SMAD4, and MSH2in patients with familial adenomatous polyposis [FAP], assisting in early detection and personalized risk assessment." (PMID 38999541, 2024).
pulmonary arterial hypertension (12 papers, 2013 to 2025). "Rare variants such as SMAD1, SMAD4, and SMAD9 associated with genetics with pulmonary arterial hypertension are also located in the cytoplasm and nucleus." (PMID 40710838, 2025). "However, the mutation N13S on Smad4 does not disrupt any of these interactions and is associated with a different disease, pulmonary arterial hypertension." (PMID 25502805, 2014).
endometrial cancer (11 papers, 2016 to 2023). Primary or metastatic malignant neoplasm involving the endometrium (mucous membrane that lines the endometrial cavity). "On the other hand, a study has been published presenting that decreased mRNA levels of SMAD2, SMAD3, and SMAD4 are frequent events, respectively in 71.4%, 78.6%, and 78.6% of analyzed endometrial cancer samples." (PMID 34501347, 2021). "Smad2 and Smad4 immunoreactivity in endometrial cancer is comparable with that observed in normal endometrium." (PMID 34501347, 2021). "SMAD2, SMAD4, and SMAD7 genes are located at the 18q21 locus, which is highly prone to the MSI or loss of heterozygosity (LOH) in endometrial cancer." (PMID 34501347, 2021). "Taken together these results strongly show that miRs-205, −146a, and −1260b contribute to enhancing proliferation and migration properties of endometrial cancer cells through Smad4 inhibition." (PMID 31293968, 2019). "The region within 18q21 where Smad4 is located is frequently deleted in endometrial carcinomas, showing its involvement in EC, however, an immunohistochemical study showed that inactivation of this gene occurs infrequently in this tumor." (PMID 31293968, 2019). "To better understand how the dysregulation of these miRs may change the behavior of endometrial cancer-derived cell line, we examined the influence of Smad4 knockdown on Hec1a cell migration." (PMID 31293968, 2019). "To gain further insights into how dysregulation of these miRs may play a role in endometrial cancer cells, we performed different assays to study the biological effects of the interaction between these miRs and their target Smad4 into endometrial adenocarcinoma-derived cell lines Hec1a." (PMID 31293968, 2019). "Certain signaling pathways were differentially targeted by miR-146a-5p in various cancers, including LIF-Stat3 when reported in the endometrium of patients with implantation failure, NOTCH 1/2 in endometrial carcinoma, and the EGFR, NF-κB, TGF-β, and SMAD4 pathways in other tumor types." (PMID 37240034, 2023). "The literature data indicate that SMAD2 and SMAD4 expression is not altered in endometrial cancer when compared to normal endometrium." (PMID 34501347, 2021).
rectal cancer (11 papers, 2012 to 2025). A primary or metastatic malignant neoplasm that affects the rectum. "The results demonstrate that SMAD4 mutations might serve as a biomarker for predicting the response of rectal cancer to nCRT." (PMID 36142267, 2022). "BRAF, FBXW7, PTEN, and SMAD4 mutations were observed in 20.7% of patients with rectal carcinoma." (PMID 36142267, 2022). "Inconsistent with our findings, one clinical study examining an Eastern European cohort of genomically undefined colon and rectal cancers found that increased levels of cytoplasmic TGFβ1 and loss of SMAD4 were associated with reduced tumor-infiltrating macrophages." (PMID 27270652, 2017). "Secondary rectal cancer tumors had distinct molecular features, including lower mutational burden, lower frequency of APC alterations, higher rates of SMAD4 inactivation, and increased rates of frameshift and inframe deletions." (PMID 40100215, 2025). "Our study confirmed the decreased expression of SMAD4 in rectal cancer." (PMID 23158542, 2012).
ductal adenocarcinomas (10 papers, 2003 to 2025). "For SMAD4, homozygous deletion mutations have been identified in invasive ductal carcinomas and it still remains a possibility that biallelic inactivation due to germline homozygous deletions could be playing a significant role in tumorigenesis." (PMID 21835029, 2011). "For example, genetic changes common in ductal adenocarcinomas such as mutations in KRAS and loss of SMAD4/DPC4 were found to be infrequent in PNECs." (PMID 26854147, 2015). "We then examined Smad4 expression in benign human breast and ERα-positive infiltrating ductal carcinoma tissue." (PMID 19943940, 2009). "In contrast, Smad4 are weekly expressed and largely restricted in the cytoplasm of cancer cells from 8 of 12 cases with infiltrating ductal carcinoma." (PMID 19943940, 2009). "The data also clearly indicate a dynamic change of Smad4 expression from benign breast ductal tissue to infiltrating ductal carcinoma." (PMID 19943940, 2009). "There appears a dynamic change of Smad4 expression from benign breast ductal tissue to infiltrating ductal carcinoma." (PMID 19943940, 2009). "The residual benign ductal epithelial cells surrounded by infiltrating ductal carcinoma highly expressed Smad4 in both cytoplasm and nucleus, while the expression of Smad4 was markedly decreased and largely restricted to cytoplasm in ERα-positive infiltrating ductal carcinoma." (PMID 19943940, 2009). "In contrast to gland-forming NETs, well-differentiated ductal adenocarcinomas form glands with much more irregular contours, and tumor cells are positive for CEA and, in about 55–80% of cases, negative for SMAD4/DPC4." (PMID 40668487, 2025).